IL6 (interleukin 6)
Diseases named in the same sentence as IL6 in open-access papers (continued):
Sharing a sentence is not in itself a finding about the gene and the disease.
cancer (continued). "Additionally, we showed that ET conditions attenuated the IL-6 expression in co-cultured cells (4T1 or CT26 and MoET) compared to the IL-6 level measured in the co-culture of cancer cells with macrophages exposed previously to LPS once (i.e., for 4T1 and CT26, p < 0.001)." (PMID 37894480, 2023). "IL6 belongs to the family of IL (interleukin)-6-type cytokines, which could be secreted by myriads of cells, including monocytes, fibroblasts, endothelial cells, keratinocytes, and cancer cells." (PMID 37454220, 2023). "For these reasons, IL-6 could be studied as a biomarker of cancer stage." (PMID 37173873, 2023). "Likewise, IL-6 and IL-8 were also highly expressed in malignant tumor tissues." (PMID 36693957, 2023). "5-FU-miR-15a was also shown to significantly inhibit the expression of Yap1, Bcl2, Il6, and Mmp9, both alone and during treatment with TGFβ1 in murine and human Pancreatic Stellate Cells, suggesting the reduced proliferation and migration of pancreatic stellate and cancer cells." (PMID 38139352, 2023). "Moreover, we also observed a similar prognostic value of IL-6 in tumors across The Cancer Genome Atlas (TCGA) Pan-Cancer dataset, suggesting that the role of IL-6 in promoting cancer progression and hindering patient survival is common among a wide range of cancers." (PMID 37696858, 2023). "Hence, studies show that IL-6 may help sustain cancer stem cell populations and increase EMT, whereas IL-4, CCL-2 and exosomal miRNA from cancer cells cause M2 polarization of TAMs." (PMID 37173970, 2023). "Other work demonstrates that activation of certain cytokine/chemokine pathways, for example those involving IL‐6 or IL‐8, can promote the recruitment and proliferation of myeloid‐derived suppressor cells (MDSCs), which can contribute to the dysfunction of T cells in cancer immunity." (PMID 37062076, 2023). "Similarly, given the precedent of successful targeted inhibition of IL-6 signaling in people diagnosed with certain chronic inflammatory conditions and different forms of cancer, similar approaches could be tested in cats with FCGS." (PMID 37205490, 2023). "Hence, we proposed that immune-suppressive stroma could be vigorously promoted through a positive feedback loop of PDGFB signaling and IL6 signaling between cancer cells and CAFs." (PMID 37658364, 2023). "Circulating GDF15 and IL6, derived from cancer cells, could perhaps activate brown fats." (PMID 37886942, 2023). "Moreover, dysregulated IL-6 expression is frequently observed in cancer." (PMID 36357631, 2023). "Dox-mediated DNA damage induced STING-mediated NF-κB activation in TNBC cell lines resulting in the induction of IL-6 secretion which could activate pSTAT3 leading to cancer cell survival enhancement and an immune-suppressive mechanism by PD-L1 expression induction." (PMID 37480115, 2023). "In addition to the burn injuries, increased levels of circulatory IL-6 are present in other medical conditions, including sepsis, COVID-19, diabetes mellitus, cancer, chronic obstructive pulmonary disease, myocardial failure, and end-stage kidney disease." (PMID 36588738, 2022). "Consequently, blocking or inhibiting IL-6 signaling pathways may provide an interestingly therapeutic target to re-sensitize cancer cells to immunotherapies." (PMID 36405719, 2022). "Thus, IL-6 and TNFα SNPs could be potential markers of baseline pain intensity and opioid dose requirements in pediatric cancer patients." (PMID 35335997, 2022). "Interestingly, IL-6 knockdown in cancer associated fibroblasts (CAF) increased IFN-γ on CD8-postive T cells and IL-6 blockade could reverse anti-PD-L1 resistance in an HCC mouse model." (PMID 35267462, 2022). "Moreover, STAT3 is closely associated with IL-6, AMPK, or ERK in cancer progression." (PMID 35742904, 2022). "Also an IL-6 dose-dependent increase in HGF was found in cancer patients." (PMID 36389782, 2022).
cancer (continued). "Thus, it is evident that the role of IL-6 and other inflammatory mediators in cancer progression is profoundly complex, and it is likely too simplistic to suggest that the withdrawal of IL-6 signalling from cancer cells via exercise training is sufficient to stifle cancer growth." (PMID 35359426, 2022). "Cancer cells can also change the epigenome of MDSCs with respect to the expression of IL-6, whereby Krüppel-like factor 4, a transcription factor with zinc fingers, regulates the production of IL-6 in DCs through the acetylation of histones, thereby modifying the pattern of Treg accumulation." (PMID 35267487, 2022). "Thus, short‐term IL‐6 exposure may inhibit cancer growth through endocrine/paracrine signalling, while chronic exposure may lead to autocrine cell growth stimulation by inducing cells to acquire endogenous IL‐6 production." (PMID 35213038, 2022). "However, one should bear in mind that blood IL-6 could be derived from multiple types of cells other than cancer cells, such as B cells, macrophages, and fibroblasts." (PMID 35197546, 2022). "Additionally, decreased albumin levels demonstrate an increased inflammatory status with elevated levels of cytokines, such as tumor necrosis factor-alpha, IL-1, and IL-6, which may contribute to cancer progression." (PMID 35915403, 2022). "Hence, the establishment of a TIMP-1/IL-6 loop to increase STAT3 activity may depend on cancer type and CAF subtype." (PMID 36291767, 2022). "IL6 is a well-known pro-tumoral autocrine factor for RCC cells; moreover, a recent report demonstrated that epithelial memory is induced by inflammatory insults and that may promote pancreatic tumorigenesis mainly through the activity of immune-derived interleukin-6 directed onto cancer cells." (PMID 35814450, 2022). "In addition, the experiment also verified that cancer cells expressing IL–6 and IL–1β could form a more proliferative CTC–neutrophils clusters than those lacking IL–6 and IL–1β receptors." (PMID 36059616, 2022). "In conclusion, sleep disruption may lead to abnormal inflammatory responses as evidenced by the upregulation of proinflammatory cytokines (especially IL-6 and CRP), which are potential risk factors for several cancers, including ovarian, brain, breast and colorectal cancers." (PMID 35246220, 2022). "Elevated levels of cytokines such as tumor necrosis factor alpha (TNF-α), interleukin (IL)-6 and IL-1β, a lipid molecule prostaglandin E2 (PGE2), and chemokines such as CXC chemokine ligand 1 (CXCL1) and CXCL2 in the serum of CRC patients were associated with cancer development and progression." (PMID 35954156, 2022). "Accordingly, blocking IL-6 or inhibiting related signaling pathways, independently or in combination with conventional anti-cancer therapies, may be a potential therapeutic strategy in the treatment of cancer." (PMID 35884907, 2022). "Moreover, the circulating H3Cit level was significantly correlated with high levels of IL-8 and IL-6 in the plasma of the cancer patients, which is important because these two cytokines have been shown to reflect the pathological progression and prognosis of cancer patients." (PMID 36365233, 2022). "Indeed, since chronic inflammation is well known to play a critical role in cancer progression, development, and survival, the finding of decreases in a variety of cytokines (particularly IL-6, and TNF-α) may have similar implications." (PMID 35935260, 2022). "Interestingly, the high-risk score group also comprised significant enrichment of unfavorable cancer-related hallmark gene sets, such as “ANGIOGENESIS”, “E2F_Target”, “IL2_STAT5 signaling”, “IL6_JAK_STAT3 signaling”, “MTORC1 signaling”, “MYC_TARGETS_V1” and “PI3K_AKT_MTOR signaling”." (PMID 37304008, 2022).
cancer (continued). "More specifically, myokines could be divided into those that may directly influence the TME, such as secreted protein rich in cysteine (SPARC), oncostatin M, and irisin; and those that may indirectly affect cancer evolution by enhancing the antitumor immune response, such as IL-6, IL-7, and IL-15." (PMID 35454797, 2022). "Furthermore, result showed that IL-6-induced cancer cell invasion is dependent on the activation of the Raf/MAPK pathway and that resveratrol may suppress this pathway activation." (PMID 35566016, 2022). "Similarly, a decrease in IL-6-induced STAT3 mitochondrial localisation leads to mitochondrial oxidative stress, loss of mitochondrial membrane potential, and subsequent apoptosis of cancer cells." (PMID 36429126, 2022). "Finally, SASP components might be of particular interest due to their potential role in cancer cell dissemination in ovarian cancer, specifically through the expression of IL-6, IL-8 and MMPs." (PMID 36497411, 2022). "Similarly, mitochondrial dysfunction, marked by reduced mitochondrial biogenesis and increased mitochondrial fission proteins, has been reported in an IL-6 induced mouse model of cancer cachexia, suggesting a role for IL-6 in mediating the oxidative stress in this process." (PMID 35204066, 2022). "Tocilizumab and sarilumab, two monoclonal antibodies against IL-6 receptor (IL-6R), suppress IL-6 signaling pathway and are recommended for the treatment of rheumatoid arthritis and cytokine storm caused by chimeric antigen receptor T (CAR-T) cell therapy in cancer patients." (PMID 36182930, 2022). "IL-6 stimulates adhesion and matrix molecules such as N-cadherin, vimentin, snail, twist and E cadherin and also stimulates stem cell recruitment and self-renewal which all together contribute towards not only cancer development but also its progression and distant spread." (PMID 34951691, 2022). "For example, it is important to note that IL-6 and IL-1β-producing TAMs, possibly M1-like, promote tumor growth through the production of these cytokines, which shows that M1 TAMs are not always able to precisely exert their antitumor functions during cancer progression." (PMID 36532078, 2022). "Cancer-elicited inflammation promotes not only the generation of monocytes in the bone marrow in response to the myeloid-lineage growth factors GM-CSF, G-CSF and interleukin-6 (IL-6), but also drives extramedullary monopoiesis in the spleen by mobilized HSPCs and MyP." (PMID 35008390, 2022). "Notably, FRC derived IL-6 is known to be able to affect the fate of T cells during T cell priming in the lymph node suggesting this as a possible mode of T cell modulation by CAFs in cancer." (PMID 35479076, 2022). "Therefore, serum CRP levels in patients with cancer might represent the biological behavior of cancer tissues because of the close relationship between IL-6 and CRP." (PMID 36096761, 2022). "Cytokines—i.e., IL-6, IL-8, IL-11, IL-27, IL-31—are small immunological proteins important in autocrine, paracrine, and endocrine signaling processes that influence inflammation, cell growth and proliferation, cell and matrix interactions, and disease progression in cancer." (PMID 35326569, 2022). "CAF‐produced IL6 also could promote cancer metastasis through TGFβ‐induced EMT and STAT3 signal." (PMID 35978854, 2022). "Fortunately, the appropriate administration of SPN(NIR-3) and laser irradiation could result in the proper uplift of intracellular oxidative stress, leading to ICD, followed by the release of DAMPs from cancer cells to induce DCs maturation and upregulate cytokines (IL-6 and TNF-α) expression." (PMID 36276646, 2022). "Furthermore, the anti-IL-6 mAb, siltuximab, is being tested in clinical trials for several cancers such as large granular lymphocytic leukemia (LGLL), metastatic pancreatin cancer, and MM, both alone and in combination therapy (NCT05316116; NCT04191421; NCT03315026)." (PMID 36140335, 2022).
cancer (continued). "The polymorphism of four genes examined in the North-Italian population (IL-6 (G > C, rs1800796), IL-10-1082 (G > A, rs1800896), TNF-α-308 (G > A, rs1800629), and TGFβ1 codon 10 (T > C, rs1800471)) was connected with an increased duration of inflammation and cancer risk." (PMID 35163247, 2022). "Furthermore, the decrease of expression of inflammatory genes such as IL-β, IL-6, and TNF-α could provide protection from the injury caused by the carcinoma associated inflammatory response." (PMID 35163250, 2022). "Thus, cancer-cell induced IL-6 release in designated microenvironments may help to disguise immunogenic cell death states." (PMID 34711820, 2021). "IL-6 and chemokine CXCL-9 are important for the growth and development of tumors, but it is unclear whether baseline cytokine and chemokine levels are associated with overall cancer survival and the development of irAEs." (PMID 34805229, 2021). "However, IL-6 is a multifunctional cytokine that has pro- and anti-inflammatory properties, and can be affected by different conditions such as exercise, aging, certain cancers, frailty, and chronic inflammatory response." (PMID 33446739, 2021). "However, in certain cancer cells types, IL6 signaling was shown to be anti-proliferative." (PMID 34411141, 2021). "IL-6 may affect the development of cancer through influencing anti-apoptotic pathways." (PMID 33663382, 2021). "As previously confirmed, insulin not only influences malignant cancer cells promotion directly via some signaling pathways, but also induces carcinogenic effects indirectly through production of some inflammatory cytokines such as interleukin-6 (IL-6) and C-reactive protein (CRP)." (PMID 34271937, 2021). "Furthermore, IL-6 was also reported to be a key mediator in cancer-related cachexia." (PMID 34578883, 2021). "Furthermore, IL-6 could promote the autophagic activity of target cancer cells after engulfing CTLs, so that protect them from toxic effects and help them survive immune surveillance." (PMID 33868318, 2021). "Mechanistically, IL6 and HH/GLI signaling integration occur at the level of cis-regulatory sequences by co-binding of GLI and STAT3 to common HH-IL6 target gene promoters and HH-IL6 pathway combinatorial blockade could efficiently arrest cancer growth in BCC patients." (PMID 33494284, 2021). "Thus, IL6 is an effective marker for predicting poor prognosis in cancer patients." (PMID 34141615, 2021). "Therefore, it might be important to consider that this type of cancer expresses high levels of IL-6, inducing cachexia." (PMID 33531609, 2021). "In addition, the role of HCMV in promoting STAT3 phosphorylation suggested that HCMV may participate in the occurrence and development of malignant tumors through the IL-6/JAK/STAT3 signaling pathway." (PMID 34194533, 2021). "Also, hepcidin levels may be regulated by cancer-induced inflammation through IL-6 dependent and independent pathways." (PMID 33842333, 2021). "However, whether RIPK4 induces EMT through the IL-6/STAT3 pathway still needs to be explored in malignant epithelial cancers, particularly in OC." (PMID 33855091, 2021). "Interestingly, our data suggest that IL-6 blockade may be able to decouple auto-immune and anti-cancer immune responses, potentially increasing anti-cancer immunity while treating auto-immune toxicity." (PMID 34711820, 2021). "Interestingly, since CoQ10 has been reported to decrease the circulatory level of these cytokines, the deficit in CoQ10 status reported in cancer patients may contribute to the high levels of IL-6 and TNF detected in this disease." (PMID 34064686, 2021). "Similarly, IL-6 also induces glycolytic enzyme expression in cancer cells via signal transducers and activators of transcription 3 (STAT3)/c-Myc signaling, and correlated with tumorigenesis, which together suggests that inflammation can induce metabolic reprogramming and promote cancer progression." (PMID 33514004, 2021).
cancer (continued). "We investigated the kinetics of CRP, PCT, IL-6 and MR-proADM in a cohort of consecutive febrile patients with cancer in order to test the hypothesis that higher plasma concentrations and the absence of a rapid decrease in peak values would be associated with disease severity." (PMID 34828740, 2021). "Thus, the anti-inflammatory effect of flavonoids inhibits angiogenesis of cancer cells by decreasing inflammatory cytokines such as tumor necrosis factor-alpha, interleukin (IL)-1β, and IL-6, and the anti-estrogen effect prevents metastasis of cancer cells by decreasing aromatase activity." (PMID 34578927, 2021). "However, high levels of TNF- α, IL-2R, IL-6, and IL-8 did not raise the risk of death in non-cancer patients." (PMID 33735106, 2021). "Furthermore, IL-1β induces IL-6 production by transglutaminase 2- (TG2-) expressing MCF-7 cells through NF-κB-, PI3K-, and JNK-dependent mechanisms, ultimately increasing the stem-cell-like phenotype of cancer cells associated with drug resistance." (PMID 34602858, 2021). "Moreover, the secretion of IL-6 make CAF an important mediator of EMT in cancer cells." (PMID 34094963, 2021). "IL-6 may affect cancer development by influencing anti-apoptotic pathways." (PMID 33663382, 2021). "However, IL-6 signaling often induces cancer progression in both autocrine and paracrine manners." (PMID 33923292, 2021). "In addition, IL-6 has been reported to induce resistance to cancer therapies and anoikis." (PMID 34361105, 2021). "Additionally, IL-6 is closely related to cancer-promoting cellular reprogramming and EMT80." (PMID 34916607, 2021). "Two of the genes evaluated showed elevated protein expression in tumors from IL-6-deficient Eμ-myc mice: BIM [BCL2L11], a BCL-XL and BCL2 interacting mediator of cell death, and PTEN, a phospholipid phosphatase and tumor suppressor gene mutated in many human cancers." (PMID 33651821, 2021). "GSEA analysis of the pre-ranked list using the cancer ‘Hallmarks’ collection from MSigDB identified few differentially regulated sets, but showed the gain of inflammatory response genesets in IL-6 KO samples, suggesting a global difference in immune states between WT and IL-6 KO mice." (PMID 34711820, 2021). "Myriad studies have revealed that exposing stromal fibroblasts to cancer-targeted genotoxic agents resulted in significant upregulation of inflammatory factors or cytokines including interleukin (IL)-1β, matrix metalloproteinase-3, IL-6, WNT16B, and IL-813,20,26,29." (PMID 34108603, 2021). "Cancer-associated fibroblasts (CAFs) are a dominant stromal cell type in the TME that are activated from resting fibroblasts via the NF-κB and JAK-STAT pathways once cancer cells or immune cells release signaling molecules such as TGFβ, RTK ligands, IL1β and IL6." (PMID 34202411, 2021). "Our results suggest the relevance of epigenetic regulation of IL6 signaling and pave the way for further studies to validate these findings and to assess the prognostic and therapeutic predictive value of these epigenetic markers on the clinical outcome and survival of cancer patients." (PMID 34576335, 2021). "Furthermore, in human samples, stromal IL-6 expression was significantly correlated with the EMT status of cancer cells and with prognosis in patients, thus indicating that stromal IL-6 secreted from CAFs enhanced EMT signaling and induced resistance against chemotherapy or chemoradiotherapy." (PMID 33673405, 2021). "In addition, inhibited autophagy activation by CQ, leading to the blockage of autophagic flux, thereby decreased the amount of IL-6, and inhibited STAT3 expression, which caused the shift from autophagy to apoptosis and increased the sensitivity of cells to cancer therapy." (PMID 34771150, 2021). "In addition, increased serum IL-6 expression stimulates the growth of cancer cells." (PMID 33854585, 2021). "Hence, the down-regulation of the IL-6/STAT3 signalling is critical in cancer management." (PMID 34078370, 2021).